LIN28A (lin-28 RNA binding posttranscriptional regulator A)
Diseases named in the same sentence as LIN28A in open-access papers (continued):
Sharing a sentence is not in itself a finding about the gene and the disease.
leukemia (10 papers, 2014 to 2025). A malignant (clonal) hematologic disorder, involving hematopoietic stem cells and characterized by the presence of primitive or atypical myeloid or lymphoid cells in the bone marrow and the blood. "We performed LIN28 co-IP and mass spectrometry (MS) on lysates from embryonic stem cells and leukemia cell lines with high levels of LIN28A or LIN28B expression." (PMID 38875287, 2024). "LIN28A also regulates the stemness of cancer stem cells and is thought to have an oncogenic role in gastrointestinal cancer and leukemia." (PMID 28587210, 2017). "However, leukemia did not develop in mice transplanted with Lin28a knockdown HSCs, suggesting that Lin28a is necessary, but not sufficient, for miR-125-driven leukemogenesis." (PMID 25477897, 2014). "By contrast, no sign of leukemia was observed in six mice transplanted with ITD/ITD lin− cells with Lin28a knockdown 4 months after transplantation, indicating a cooperative effect between Htra3, Lin28a, and ITD/ITD in AML induction." (PMID 34732858, 2022).
prostate carcinoma (10 papers, 2011 to 2024). A carcinoma that arises from epithelial cells of the prostate gland. "Moreover, let-7 has been found to maintain the cancer stem-like cell (CSC) phenotypes of prostate cancer, let-7 expression is controlled by LIN28A and LIN28B, and loss of let-7 increases the expression of SOX2 and promotes the cell transformation and expansion of prostate CSCs." (PMID 37596700, 2023). "(OCT4, 19%; SOX2, 29%; NANOG, 14%; LIN28A, 9%; KLF4, 29%); the SOX2 and KLF4 genes were amplified predominantly in prostate cancer." (PMID 30287838, 2018). "Unfortunately, there is not much evidence that LIN28A or LIN28B are actually expressed in normal tissues or in prostate cancer cells (e.g., The Cancer Genome Atlas, TCGA, or other datasets)." (PMID 32645914, 2020). "Another obscure aspect of let-7 regulation by LIN28A suggests that we do not understand much about this miRNA family: LIN28A can suppress let-7 expression and is mentioned as a mediator of the “reduced” let-7 activity in prostate cancer." (PMID 32645914, 2020).
embryonal tumors (9 papers, 2012 to 2024). "In brain tumors, LIN28A expression was described in gliomas, atypical teratoid/rhabdoid tumors (AT/RT) and embryonal tumors with multilayered rosettes (ETMR)." (PMID 34801069, 2021). "DFMO, an inhibitor of LIN28A/B, has been identified as a potential treatment option for embryonal tumors." (PMID 35008302, 2021). "These were confirmed to be diffuse midline gliomas with H3K27M mutation by immunohistochemistry (n = 4), glioblastoma (n = 3), and embryonal tumor with multilayered rosettes with LIN28A protein overexpression (medulloepithelioma phenotype, NEC; n = 1)." (PMID 33637807, 2021). "In fact, Lin28a is a marker of rosette‐forming embryonic tumors, suggesting a potential mechanistic link between the formation of rosettes in Rx‐Dicer mutant embryos and certain types of pediatric brain tumors." (PMID 32985705, 2020). "LIN28A overexpression has been identified in malignant brain tumors called embryonal tumors with multilayered rosettes (ETMR) but its specific role during brain development remains largely unknown." (PMID 34801069, 2021). "According to a large study, the strong expression of Lin28A in ETMRs statistically relates to poorer outcomes than those of negative or focal expression in other CNS embryonal tumors." (PMID 36353532, 2022). "Embryonal tumors with multilayered rosettes (ETMRs) which otherwise lack rosettes, a medulloepithelioma component, and neurocytic/neuropil-rich areas could also resemble embryonal tumors with BRD4::LEUTX fusions, but they are generally negative for OLIG2 and positive for LIN28A." (PMID 38500181, 2024).
Insulin resistance (9 papers, 2013 to 2022). Increased resistance towards insulin, that is, diminished effectiveness of insulin in reducing blood glucose levels. "Such a role of the let-7/Lin28 axis in regulation of glucose metabolism is further demonstrated in transgenic mice with muscle-specific loss of Lin28A or overexpression of let-7, which results in insulin resistance, hyperglycemia and impaired glucose tolerance." (PMID 34572067, 2021). "In addition, Lin28a overexpression was associated with increased insulin sensitivity and glucose metabolism, while a depletion of Lin28a resulted in insulin resistance and glucose intolerance." (PMID 23939427, 2013). "As Lin28a directly promotes HMGA1 translation, it has been postulated that in muscle-specific Lin28a knockout mice, insulin resistance is, at least in part, due to reduced HMGA1 levels and consequently impaired INSR expression." (PMID 30034366, 2018).
seminoma (9 papers, 2013 to 2025). A radiosensitive malignant germ cell tumor found in the testis (especially undescended), and extragonadal sites (anterior mediastinum and pineal gland). "Another study in seminomas indicates that the overexpression of PRAME and its interaction with Lin28A support pluripotency networks and expression of reprogramming markers, such as DPPA3, Nanog, Oct3/4, ZSCAN10, and PRDM14." (PMID 40961095, 2025).
neuroblastoma (8 papers, 2016 to 2024). Neuroblastoma (NB) is the most common solid, extracranial childhood tumor. "Overexpression of LIN28A gene has been linked to the development of multiple human malignancies, but the relationship between LIN28A single nucleotide polymorphisms (SNPs) and neuroblastoma susceptibility is still under debate." (PMID 31747721, 2020).
brain tumors (7 papers, 2013 to 2025). "As Lin28A has been shown to be associated with brain tumors and neural progenitor proliferation, we next aimed to analyze the influence of Lin28A overexpression on cell proliferation within the cerebral cortex." (PMID 34801069, 2021). "For example, LIN28A, a known pluripotent factor and oncogene, has also been found to be a prognostic and diagnostic marker for primitive neuro-ectodermal tumors and other rare embryonal brain tumors." (PMID 26398939, 2015). "LIN28A is overexpressed in embryonal brain tumors which show low correlation between transcriptome and proteome signatures." (PMID 40680886, 2025). "We therefore constitutively overexpressed Lin28A in hGFAP-positive neural precursor cells to study its impact on brain development and for brain tumor formation in vivo." (PMID 34801069, 2021). "As part of a screen of a series of pediatric brain tumors for LIN28A expression, we identified high level LIN28A expression in AT/RT samples by immunohistochemistry." (PMID 25638158, 2015). "In brain tumors, we recently reported that LIN28A promotes invasion and tumorigenesis in glioblastoma in part through upregulation of HMGA2." (PMID 25638158, 2015). "Recent papers have described increased expression of LIN28A in primitive neuro-ectodermal tumors and atypical teratoid rhaboid tumors, which are aggressive pediatric brain tumors." (PMID 23846349, 2013). "As ETMRs show an overexpression of Lin28A, we wanted to examine whether Lin28A is sufficient to drive embryonal brain tumors in vivo." (PMID 34801069, 2021). "Lin28A is expressed during early embryonal development and in embryonal brain tumors, such as ETMR." (PMID 34801069, 2021). "We asked whether an overexpression of LIN28A in such cells might affect brain development or result in the formation of brain tumors." (PMID 34801069, 2021). "We asked whether an overexpression of Lin28A in neuronal progenitor cells in vivo might affect brain development or result in the formation of brain tumors." (PMID 34801069, 2021). "The cellular reprogramming factor LIN28A promotes tumorigenicity in cancers arising outside the central nervous system, but its role in brain tumors is unknown." (PMID 23846349, 2013). "However, the specific role of LIN28A during embryonal and postnatal brain development and for brain tumor formation still remains unknown." (PMID 34801069, 2021). "The oncogenic proteins LIN28A and CTNNB1 have been reported in embryonic brain tumors." (PMID 40680886, 2025). "In conclusion, we show that Lin28A overexpression transiently increases proliferation of neural precursor cells but it is not sufficient to drive brain tumors in vivo." (PMID 34801069, 2021). "Constitutive overexpression of LIN28A in hGFAP-cre::lsl-Lin28A (GL) mice led to a transient increase of proliferation in the cortical VZ at embryonic stages but no postnatal brain tumor formation." (PMID 34801069, 2021). "Taken together, we show that Lin28A overexpression was not sufficient to drive brain tumors in vivo but impacted on spine morphogenesis." (PMID 34801069, 2021). "However, a sole LIN28A overexpression in neural precursor cells does not lead to brain tumor formation, suggesting that other factors are required to initiate tumor growth." (PMID 40680886, 2025). "While hGFAP-positive precursor cells in the ventricular zone have been shown as a potential cell of origin for ETMR, a sole constitutive overexpression of Lin28A in these cells was not sufficient to drive brain tumor development, neither in the forebrain nor hindbrain." (PMID 34801069, 2021). "Overexpression of Lin28A in neural precursor cells does not lead to brain tumor formation." (PMID 34801069, 2021).
breast tumor (7 papers, 2012 to 2018). "Lin28A has been reported to promote cell proliferation in embryonic stem cells and breast tumor cells." (PMID 29949865, 2018). "Our findings suggest that there are a significant number of ER−/Her2+ breast tumors express Lin28A and AR and Lin28A can activate AR expression." (PMID 27494865, 2016). "In this study, we found that Lin28A can activates androgen receptor(AR) via regulation of c-myc and promote ER-/Her2+ breast tumor growth." (PMID 27494865, 2016). "We initially determined Lin28A and AR expression in ER-/Her2+ and ER-/Her2- breast tumor cells lines." (PMID 27494865, 2016). "It has been reported that Lin28A is able to promote cell proliferation in embryonic stem cells and breast tumor cells." (PMID 24603866, 2014). "For example, Lin28A was expressed in HER2-overexpressing breast tumour but Lin28B was expressed in triple-negative breast tumour." (PMID 24386298, 2013). "Until now, Lin28A and Lin28B expression has been reported distinctively or exclusively in several tumours including gastric, colorectal, gonad, hepatocellular and breast tumours distinctively or exclusively." (PMID 24386298, 2013). "The results indicated that higher expression of Lin28A may enhances expression of AR and promotes tumor growth of ER-/Her2+ breast tumor cells via regulation of c-myc in vivo." (PMID 27494865, 2016).
Wilms tumor (7 papers, 2016 to 2024). An embryonal neoplasm characterized by the presence of epithelial, mesenchymal, and blastema components. "LIN28A gene overexpression has been reported to be involved in various human malignancies, while its roles in Wilms tumour risk are still under investigation." (PMID 31338973, 2019). "Interestingly, Dis3l2, which plays an important role in the Lin28a/let-7a pathway, is frequently mutated in Wilms’ tumor and causes the Perlman syndrome of overgrowth." (PMID 27881476, 2017).
glioblastoma (6 papers, 2013 to 2021). The most malignant astrocytic tumor (WHO grade IV). "Compared to the expression of Lin28A in NBTs (n = 37), Lin28A was upregulated in glioblastoma brain tissues (n = 582)." (PMID 32527996, 2020). "We have previously identified high-level expression of LIN28A and LIN28B in approximately 30 percent of pediatric and adult glioblastoma." (PMID 25638158, 2015).
diabetes (5 papers, 2014 to 2022). "Genetic factors may be also involved, as animal studies have shown that overexpression of the RNA-binding proteins Lin28a/b gene exhibits both later pubertal maturation and increased glucose uptake, which provide a possible mechanistic link between early menarche and diabetes risk." (PMID 28605451, 2018). "When overexpressed in mice, Lin28a promoted an insulin-sensitized state that resisted high-fat diet-induced diabetes." (PMID 25688987, 2015). "According to our recent preliminary data, both diabetes and ischemic insult lead to decreased expression of Lin28a, increased cardimyocyte apoptosis and impaired mitochondrial function." (PMID 25313561, 2014). "Although one of the main known roles of Lin28 is to promote tumourigenesis and metabolic diseases, the reprogramming of glucose metabolism by Lin28A/B brings advantages to the resistance to diabetes, skeletal muscle maintenance, and acceleration of tissue repair." (PMID 36230562, 2022).
lymph node metastasis (5 papers, 2012 to 2021). "High expression of LIN28A and LIN28B correlated significantly with lymph node metastasis and poor prognosis." (PMID 32828126, 2020).
acute myeloid leukemia (4 papers, 2017 to 2024). Acute myeloid leukemia (AML) is a group of neoplasms arising from precursor cells committed to the myeloid cell-line differentiation. "While some reports relate Lin28A and its homologue Lin28B to hematopoiesis and also acute myeloid leukemia, it remains unclear if differences in blood counts are direct or indirect effects of Lin28A expression in hGFAP-positive cells." (PMID 34801069, 2021). "Reactivated LIN28A or LIN28B expression almost invariably correlates with poor prognosis in many tumors, including acute myeloid leukemia, brain cancers, and NB." (PMID 38732012, 2024).
hepatoblastoma (4 papers, 2016 to 2024). Hepatoblastoma (HB) is a malignant hepatic tumor and is the most common pediatric liver cancer. "We previously found that the deletion of Lin28a and Lin28b impaired the growth of MYC-induced pediatric hepatoblastomas in vivo, but the absence of Lin28a/Lin28b did not completely eliminate their initiation, possibly due to the high levels of MYC overexpression in that model." (PMID 38875287, 2024).
atherosclerosis (3 papers, 2018 to 2024). A disease characterized by the build-up of fatty material and calcium deposition in the arterial wall resulting in partial or complete occlusion of the arterial lumen. "The underlying mechanisms involved in it were investigated and we found that expression of Lin28a was significantly increased in restenosis plaques, while it was hardly to find in atherosclerosis plaques." (PMID 32710472, 2020). "Immunohistochemical results showed that Lin28a expression was significantly higher in restenosis plaques, while little was observed in atherosclerosis plaques by calculating the percentage of positive staining area in terms of total area." (PMID 32710472, 2020). "Immunohistochemical analysis revealed that significantly higher expression of Lin28a was observed in the iliac arteries of restenosis plaques than that of atherosclerosis plaques." (PMID 32710472, 2020). "We then explored whether there existed differential expressions of Lin28a in restenosis and atherosclerosis plaques." (PMID 32710472, 2020). "In contrast to atherosclerosis, Lin28a was highly expressed in VSMCs of restenosis." (PMID 32710472, 2020). "Immunofluorescence studies showed the colocalization of Lin28a with α‐smooth muscle actin in restenosis plaques, rather than in atherosclerosis plaques, which suggested that Lin28a might be related to the unique behaviour of vascular smooth muscle cells (VSMCs) in restenosis." (PMID 32710472, 2020).
bladder cancer (3 papers, 2023 to 2025). "Transwell and scratch assays showed that overexpression of Lin28a partially reversed the inhibitory effect of hsa_circ_0000520 on cell migration and invasion, while knockdown of Lin28a partially inhibited the enhanced invasiveness of bladder cancer caused by hsa_circ_0000520 knockdown." (PMID 39237880, 2024). "Hsa_circ_0000520 acts as a scaffold, promoting the binding of UBE2V1/UBC13 to Lin28a, which facilitates the ubiquitous degradation of Lin28a in bladder cancer." (PMID 39901896, 2025). "Subsequent mass spectrometry analysis revealed Lin28a as a potential protein interacting with hsa_circ_0000520 in bladder cancer cells." (PMID 39237880, 2024). "To better illustrate the role of hsa_circ_0000520 in bladder cancer metastasis, we employed T24 cells overexpressing hsa_circ_0000520, Lin28a, or both hsa_circ_0000520 and Lin28a (luciferase-labeled)." (PMID 39237880, 2024). "After treating bladder cancer cells with a UBE2V1/UBC13 inhibitor, both ubiquitination and expression of Lin28a were affected, and UBC13 was found to interact with Lin28a, indicating that UBE2V1/UBC13 regulates the ubiquitination of Lin28a." (PMID 39237880, 2024). "In bladder cancer, the long non-coding RNA LINC01451 was found to bind directly LIN28A and LIN28B and thus provoked the proliferation, invasion, and metastasis of bladder cancer." (PMID 37304235, 2023).
medulloblastoma (3 papers, 2015 to 2017). A malignant, invasive embryonal neoplasm arising from the cerebellum. "Here, a more detailed analysis revealed that, from all alternative POU5F1 transcripts investigated, only OCT4A transcript levels significantly correlated with LIN28A expression in clinical medulloblastoma specimens." (PMID 28186969, 2017). "When we examined medulloblastoma primary tumors for comparison of LIN28A expression, we found that 24 percent of these aggressive pediatric brain malignancies (15/63 tumors) expressed increased levels of LIN28A by IHC compared to normal brain." (PMID 25638158, 2015). "LIN28B is expressed in a poor-prognosis subset of medulloblastoma, and a subtype of primitive neuroectodermal tumors has increased expression of LIN28A." (PMID 25638158, 2015). "Expression of LIN28A and POU5F1 has been correlated in medulloblastoma." (PMID 28186969, 2017).
oesophageal cancer (3 papers, 2012 to 2020). "A clinical study found that LIN28A and LIN28B were overexpressed in oesophageal cancer cells, especially on the invasive front." (PMID 32828126, 2020).
papillary thyroid cancer (3 papers, 2013 to 2021). "For instance, LIN28A loss weakened cell proliferative, migratory, and invasive abilities by increasing let-7a expression and reducing c-myc expression in papillary thyroid carcinoma." (PMID 33381451, 2020).
Parkinson disease (3 papers, 2024 to 2025). A progressive degenerative disorder of the central nervous system characterized by loss of dopamine producing neurons in the substantia nigra and the presence of Lewy bodies in the substantia nigra and locus coeruleus. "Studies in Parkinson’s disease have shown that LIN28A regulates midbrain dopaminergic (mDA) specific developmental genes for the production of healthy mDA neurons." (PMID 41473749, 2025). "Accordingly, wild type LIN28A overexpression was reported to promote the therapeutic potential of cultured neural stem cells in a Parkinson’s disease model." (PMID 38341436, 2024).
yolk sac tumor (3 papers, 2017 to 2022). A non-seminomatous malignant germ cell tumor composed of primitive germ cells. "Furthermore, LIN28A as well as its homolog LIN28B are consistently expressed in malignant germ cell tumors, including yolk sac tumors and choriocarcinomas." (PMID 35806250, 2022). "In contrast, the lowest expression of HERVK was observed in somatic differentiated GCT cells which also lack OCT4 and LIN28A whereas GCT cells with differentiation characteristics of yolk-sac tumor expressed LIN28A but not OCT4 and showed intermediate level of HERVK." (PMID 29963023, 2018).
brain cancer (2 papers, 2015 to 2024). A primary or metastatic malignant neoplasm affecting the brain. "One interesting example of the miR-10 targets that were significantly downregulated by both miR-10a and miR-10b overexpression was Lin28A, which is an extensively studied RNA-binding protein implicated in brain development and brain cancer." (PMID 26395143, 2015).
cervical cancer (2 papers, 2023 to 2024). A primary or metastatic malignant neoplasm involving the cervix. "Numerous cancer types, most notably cervical cancer, have been documented to overexpress LIN28A, however, undifferentiated stem cells are where overexpressed LIN28A is most frequently seen." (PMID 38836981, 2024).